INS (insulin)
Diseases named in the same sentence as INS in open-access papers (continued):
Sharing a sentence is not in itself a finding about the gene and the disease.
diabetes (continued). "However, patients with insulin resistance do not develop hyperglycaemia and type 2 diabetes mellitus until the pancreatic β cells fail to secrete sufficient amounts of insulin to meet the increased metabolic demand for this hormone." (PMID 29558390, 2018). "Low glycaemic index (GI) dietary intervention has demonstrated benefits in non-CF forms of diabetes, including improved insulin sensitivity, glycaemia and quality of life in both type 1 and type 2 diabetes, and it is now recommended as part of their dietary management." (PMID 30021636, 2018). "Diabetes mellitus type 1 (T1DM) is caused by the autoimmune destruction of the pancreatic beta cells whereas Diabetes mellitus type 2 (T2DM) is characterized by insulin resistance that is not sufficiently compensated by insulin secretion of the pancreatic beta-cells." (PMID 30250222, 2018). "Diabetes Mellitus is a chronic metabolic disease which occurs when the human body does not respond to the insulin that is produced insulin or when the body is not able to produce enough insulin." (PMID 30450140, 2018). "Our study sample most likely encompassed only individuals with type 2 diabetes (since a first-time diabetes diagnosis was required to have been recorded after the age of 39 years), but we did not differentiate between insulin-treated and non-insulin treated type 2 diabetes." (PMID 29386666, 2018). "Likewise, the genomic region within UPF1 gene, covering the top-ranked CpG site is associated with CTCF, Egr1, and two more transcription factors: MYC—involved in the pathogenesis of diabetes, and PU1—initiating insulin resistance as well as regulating lipolysis." (PMID 30545422, 2018). "This could potentially be problematic as consistently high insulin levels can often precede diabetes which can eventually damage the β-cell to the point where the cell can no longer produce sufficient levels of insulin to combat hyperglycemia." (PMID 30473679, 2018). "Diabetes is a chronic metabolic condition wherein the tissues either do not produce enough Insulin (insulin-independent DM/type 1) or do not effectively respond to insulin due to peripheral insulin resistance (insulin-dependent DM/type 2)." (PMID 29888148, 2018). "Although GH opposes to the effects of insulin and might produce hyperglycemia and diabetes, this is not a clear contraindication for the possible use of the hormone in the case of diabetic patients with PAD." (PMID 29346331, 2018). "Patients with type 2 diabetes mellitus (T2DM) on oral antihyperglycemic treatment, who require insulin to achieve good glycemic control, most often start insulin therapy with a basal insulin, such as insulin glargine (GLA-100; Lantus®), to control fasting blood glucose levels." (PMID 29232162, 2018). "Most respondents expressed worries about not being able to live a normal life, instead being bound to lifestyle changes (not eating sweet things) and diabetes, about relapse and the need for insulin injections, although more pronounced in the first and last interviews." (PMID 29402265, 2018). "Patient-related barriers such as inability to inject, monitor, or titrate the insulin dose, weight gain, hypoglycemia, and lack of awareness of uncontrolled diabetes can be bridged with patient education and training, support and counselling, and social marketing." (PMID 29527102, 2018). "This raises the possibility that improvement in insulin sensitivity seen with vildagliptin in those with relatively well-controlled diabetes may be a drug-specific effect, rather than a class effect of DPP 4 inhibitors." (PMID 29970184, 2018). "Insulin-dependent diabetes mellitus (IDDM/type 1 DM) is presented with either lacking or reducing of insulin segregation or completely depletion of pancreatic cells responsible for producing insulin." (PMID 29854822, 2018).
diabetes (continued). "Pre‐treatment with exosomes that had been isolated from control rats without diabetes significantly reduced cell death to 29 ± 3% (P < 0.001), which was a similar degree of protection as the positive control of insulin, which reduced death to 35 ± 5% (P < 0.001; N = 4)." (PMID 28840975, 2018). "Risk of insulin treatment was augmented in t-GADA-positive individuals (OR 4.69 [95% CI 3.57, 6.17]) compared with f-GADA-positive individuals (OR 3.86 [95% CI 2.95, 5.06]), irrespective of diabetes duration." (PMID 29619531, 2018). "Diabetes represents the high level of blood sugars due to low or no insulin production in the body." (PMID 29507651, 2018). "DM affect the reproductive function via the hormonal alternation in the HPG axis and studies revealed that the insulin expression in the testis is also affected by diabetes." (PMID 30360409, 2018). "Eight of nine individuals with GCK-MODY (including seven previously treated with insulin) stopped all diabetes treatment following their genetic diagnosis, irrespective of diabetes duration (median 1.8 [IQR 0.6–7.2] years) and BMI (median 19.8 [IQR 17.9–22.7] kg/m2)." (PMID 30229274, 2018). "Ten patients (32%) were affected by diabetes mellitus (DM), impaired fasting glucose (IFG), or impaired glucose tolerance (IGT) and treated with diet or insulin (n=5)." (PMID 30356378, 2018). "Taken together these data indicate that derivatives of L. albus have favorable effects on glucose and insulin metabolism, however the bioactive components of the Andean L. mutabilis responsible for the decrease in blood glucose in people with diabetes are not known." (PMID 30104811, 2018). "Based on the results of multiple regression analysis, patients who were not on insulin treatment and patients with short duration of diabetes might be the most likely candidates who could achieve glycemic control with only MNT and lifestyle intervention." (PMID 30671482, 2018). "Additionally, previous studies also showed that PAX4+/− mice exhibit insulin-producing β cells and do not develop diabetes, indicating that a single copy of PAX4 is sufficient to promote normal β cells development and function." (PMID 29950431, 2018). "The first point of this result is that Amygdalus lycioides could not prevent the weight reduction induces by diabetes and the second point is that Amygdalus lycioides does not have a weight gain side effect such as insulin and sulfonylurea." (PMID 29755566, 2018). "One strength of our study is that we performed a clinical investigation with detailed responses of glucose and insulin to OGTT and the association between pathophysiology of GDM and perinatal outcomes in a prospective cohort of pregnant women without prior diabetes history." (PMID 30355279, 2018). "The current study demonstrates that, in individuals who are overweight but have no history of diabetes, a qualitative change in macronutrient composition with no limit on energy intake, elicits an improvement in beta-cell function and fasting insulin resistance." (PMID 29425120, 2018). "Unlike diabetes, the metabolic syndrome condition may happen without glucose elevation (at least at initial stages) but with modifications in plasma insulin and obesity." (PMID 29614007, 2018). "Among individuals diagnosed with diabetes when older than 35 years, 56% of those who commence insulin treatment immediately do not progress to absolute insulin deficiency, and 7% of those not initially treated with insulin do progress to absolute insulin deficiency." (PMID 29199115, 2018). "Numerous previous reports have shown that adiponectin is an adipokine that exerts a potent insulin-sensitizing effect; HMW adiponectin is the more active form of the hormone and plays a more relevant role in insulin sensitivity and in protecting against diabetes." (PMID 29507597, 2018).
diabetes (continued). "Our data show that FBXO28 improves pancreatic β-cell survival under diabetogenic conditions without affecting insulin secretion, and its restoration may be a novel therapeutic tool to promote β-cell survival in diabetes." (PMID 29587369, 2018). "However, in the female group, the application of statins and AVK improved the prognosis, and the following factors had negative prognostic significance: age and diabetes requiring insulin therapy as well as lower sodium concentration." (PMID 28396904, 2018). "Generally in diabetes, the pancreas cannot produce enough insulin, or the cells of the body may not respond properly to the insulin produced." (PMID 29755562, 2018). "However, post-hoc data from the Finnish and US diabetes prevention studies showed no independent effect of the intervention on the absolute insulin secretory response once changes in insulin sensitivity were taken into account." (PMID 30200572, 2018). "Second, we could not evaluate the influence of diabetes mellitus and insulin supplementation on depression." (PMID 30288172, 2018). "Our clinical evidence further indicates that the euglycemic status maintained by RYGB might be independent of insulin and islet state in patients with diabetes." (PMID 30275974, 2018). "However, the results were similar when we restricted the analysis among untreated diabetes (without any use of insulin or other hypoglycaemic agents)." (PMID 30401889, 2018). "This may reflect a lack of resources for the AI population who may not have access to newer, non-insulin therapies for diabetes." (PMID 30283862, 2018). "However, when assessing insulin content within the first five years after diagnosis of diabetes, it was found that insulin content was unchanged in diabetic versus nondiabetic subjects; but, beyond five years, insulin content was reduced in diabetic subjects." (PMID 29854823, 2018). "Recent evidence suggests that diabetes can be remitted independent of insulin." (PMID 30275974, 2018). "Impaired insulin activity in women with polycystic ovary syndrome might differ from that seen in type 2 diabetes mellitus without polycystic ovary syndrome." (PMID 29482528, 2018). "Overall, it appears that although kisspeptin enhanced insulin secretion, in healthy individuals this did not result in altered glucose levels, but this would be interesting to investigate in patients with abnormal glucose homeostasis such as in diabetes." (PMID 29974637, 2018). "Besides, lipid contents in livers obtained from STZ-induced diabetic AdIL-4 mice (diabetes with transient IL-4 overexpression) and HFD + IL-4 mice (obesity-induced insulin resistant status with long-term IL-4 overexpression) were immunohistochemically analyzed." (PMID 30584465, 2018). "Diabetes is characterized by a relative or absolute lack of insulin that results in hyperglycaemia." (PMID 30250222, 2018). "A meta-analysis showed that isocaloric exchange of fructose for other carbohydrates could decrease the level of glycated blood proteins without affecting insulin in diabetes patients." (PMID 29848962, 2018). "With a growing prevalence of diabetes and use of insulin therapy, the lack of reimbursement for PNs may have costly implications." (PMID 29699587, 2018). "This attenuation in HSP60 expression and secretion into blood in obese people with diabetes might have resulted from chronic glucolipotoxicity rather than changes in insulin secretion." (PMID 29467719, 2018). "Moreover, the small number of endpoints available in the 34 years of follow-up limits our power to study subtypes of dementia (AD, VD, dementia with and without diabetes comorbidity) and interactions between, for example, insulin and glucose tertiles." (PMID 29997193, 2018). "Diabetes mellitus may act as a confounding factor for receiving insulin therapy, and it may be that the previously observed protective effects of diabetes mellitus in ARDS may reflect an immune-modulatory effect of medications such as insulin." (PMID 30367670, 2018).
diabetes (continued). "Importantly, in both NOD mice and BB rats, therapeutic interventions for diabetes that have shown promise, e.g., oral insulin and nicotinamide, have not been successful when tried in humans." (PMID 30599002, 2018). "First, not all the insulin signaling and other convergent transduction elements could be studied in this study to reveal complete renal molecular regulatory mechanisms in diabetes." (PMID 30602713, 2018). "However, in this study, no adjustments were made for diabetes duration, complications of diabetes, and insulin treatment." (PMID 30294299, 2018). "Multiple insulin injections are one of the main reasons for non-compliance in diabetes patients." (PMID 30410846, 2018). "Although we cannot exclude that the lack of differences between groups was due to a type II error, these findings might suggest that the anti-diabetes effects of these two operations are distinct, with a somewhat more pronounced effect by LRYGB on insulin sensitivity, and by LSG on β-cell activity." (PMID 29264780, 2018). "However, mimicking the natural secretory pattern of endogenous insulin in individuals without diabetes whilst maintaining glycemia within a normal physiological range is challenging around exercise." (PMID 29342932, 2018). "In addition, most of the patients reported that insulin use neither complicates their life (56.9%) nor is a sign of worsening of their diabetes (53.0%)." (PMID 29637064, 2018). "Particularly, the presence of insulin+/Ngn3+ cells observed on day 28 in islet/MSC+ culture confirms the role of MSCs in beta cell maturation and function, suggesting an alternative source of adult beta cells as donors for the cell replacement therapy in diabetes." (PMID 30483385, 2018). "Therefore, while insulin therapy can maintain acceptable glycemic levels and reduce diabetes-related complications, it is not a cure: the only real way to definitively treat diabetes is to restore the beta cell mass or the lost functionality of those cells." (PMID 30233489, 2018). "When blood glucose levels were well controlled from the early stage of diabetes with insulin, diabetic rats showed comparable results with nondiabetic rats in cardiac function, fibrosis, MMP expression, and ROS production, regardless of additional treatment with oral pravastatin." (PMID 29682576, 2018). "Diabetes is generally classified into two types: insulin dependent and non-insulin dependent." (PMID 29872590, 2018). "In those patients with more severe pancreatic disease, endogenous insulin secretion assessed by the UCP:Cr ratio was lower than in those without diabetes [median UCP:Cr ratio 1.1 nmol/mmol (IQR 0.6–1.5) compared to 2.1 nmol/mmol (1.4–5.6), respectively; P = 0.04]." (PMID 30094008, 2018). "Despite the fact that Asian Indians are highly insulin resistant and more prone to develop T2DM and associated vascular complications, there is lack of data on the role of lncRNAs in the clinical diabetes setting and this is the rationale behind our study." (PMID 30139387, 2018). "Furthermore, there was a direct association between FAI levels and frequency of glucose intolerance (OR = 2.480, 95% CI 1.387–4.434), even after adjusting for age, BMI, waist circumference, hypertension, fasting insulin, testosterone, SHBG, and family history of diabetes." (PMID 29707577, 2018). "Therefore, we hypothesized that the PGD2 tone in islets is high in diabetics and that GPR44/DP2 antagonism consequently would improve the insulin response to glucose in humans with T2DM." (PMID 30557325, 2018). "Diabetes mellitus (DM) is a combination of heterogeneous disarray commonly presenting with the incidence of hyperglycemia and glucose intolerance, as a result of lack of insulin, defective insulin action, or both." (PMID 29670899, 2018).
diabetes (continued). "In fact, two studies reported protective associations between carbohydrate intake and DR; however, these results should be viewed with caution, as they did not adjust for important confounders such as duration of diabetes, insulin use, the quality of carbohydrates (e.g. high vs low glycemic index)." (PMID 29324740, 2018). "Although diabetes duration did not change the beta-estimate for diabetes or insulin with > 10% for any of the proteins, we had no power to investigate duration/dose of insulin exposure and the effect on tumor protein expression." (PMID 29486734, 2018). "Since these studies had no data on insulin treatment among women with diabetes and the duration and severity of diabetes might differ between studies, it is hard to explain differences between their results and ours." (PMID 29486734, 2018). "Diabetes may result mainly from lack of insulin production (type 1 diabetes) or insufficient insulin and insulin resistance (type 2 diabetes), both influenced by genetic and environmental components." (PMID 29867762, 2018). "For many years, it was tacitly accepted that glucagon might play a role, but that the lack of insulin was believed to be the predominant hyperglycemic factor in diabetes, and this remained textbook dogma." (PMID 28323959, 2017). "Furthermore, our results suggest that the protective effect of diabetics occurs regardless of type of medication being taken, although subjects on insulin have slightly more protection from UFs." (PMID 28399866, 2017). "Our aim was to investigate whether insulin and non-insulin treated women with diabetes develop specific clinicopathological breast cancer subtypes compared to women without diabetes." (PMID 28076434, 2017). "Conventional therapy for diabetes based on exogenous insulin or oral agents may control and delay, but not prevent, disease-related complications." (PMID 28758130, 2017). "Moreover, given our study results, extreme obesity with a cut-off BMI value exceeding 26–28 kg/m2 facilitates insulin secretion leading to overt diabetes via insulin resistance regardless of GH therapy, despite the effect of PWS." (PMID 28854950, 2017). "In addition, diabetes resulted in a significant increase in PTM (oxidation, phosphorylation, and acetylation) of proteins in the kidney and aorta and this effect was partially reversed by insulin treatment." (PMID 29121074, 2017). "We note, however, that diabetes and NCDs in general do have a lower funding profile and health system response in Nepal compared to infectious diseases so perhaps the unchanging, but low volume of insulin trade during the blockade is not surprising." (PMID 28830500, 2017). "This legislative change appears to have influenced further changes in ADEA and the diabetes educator workforce, as evidenced by the change of wording, predominantly in the standards of practice documents, which, after 2000, appeared to place less emphasis on the RN CDE’s role in adjusting insulin." (PMID 28702089, 2017). "The “Cardiovascular Outcomes in Participants with Type 2 Diabetes Mellitus” study, which compares CV outcomes of several drug classes (SGLT-2 inhibitors, GLP-1 RAs, DPP-4 inhibitors, Thiazolidinedione, Sulfonylureas and Insulin) could give further insight into this question." (PMID 29020969, 2017). "In addition it should be noted that for diabetes it was often said that General Practitioners were not able to treat diabetes and that they were “scared” of treating diabetes, especially using insulin." (PMID 28298226, 2017). "Although we obtained the same level of glycemic control of diabetes, assessed by glucose and fructosamine levels, between the SC vs. IP insulin-treated groups, 11β-HSD1 gene expression and activity were significantly decreased only in the IP insulin-treated group in liver." (PMID 28458655, 2017). "There are three types of diabetes: (i) type 1 DM in which pancreas fails to produce insulin." (PMID 29222671, 2017).